RNU2-26P (RNA, U2 small nuclear 26, pseudogene)
Gene: Small nuclear RNA gene on chromosome X (91,798,093 to 91,798,283, forward strand). Ensembl gene ENSG00000222440.
Homologues: Orthologues: chimpanzee U2 (100% identical), macaque U2 (88% identical), guinea pig U2 (75% identical), mouse Gm26020 (75% identical), rat LOC120099513 (75% identical). Paralogues in human: RNU2-57P (99% identical), U2 (90% identical), U2 (87% identical), RNU2-6P (87% identical), RNU2-4P (85% identical), RNU2-2 (84% identical), RNU2-59P (84% identical), RNU2-36P (83% identical), RNU2-64P (83% identical), RNU2-3P (83% identical), RNU2-48P (83% identical), RNU2-61P (83% identical), and 67 more.